SOX9 (SRY-box transcription factor 9)
Diseases named in the same sentence as SOX9 in open-access papers (continued):
Sharing a sentence is not in itself a finding about the gene and the disease.
breast tumors (13 papers, 2014 to 2026). "On the other hand, higher expression of cytoplasmic-SOX9 in breast tumors was significantly associated with ER-status and decreased overall survival." (PMID 31057614, 2019). "Besides, higher expression of cytoplasmic-SOX9 in human breast tumors is significantly associated to ER-status and to decreased overall survival." (PMID 31057614, 2019). "Sox9 expression was analysed in a cohort of 30 human primary breast tumours and adjacent normal breast tissue from the same patients." (PMID 30622340, 2019). "Recently, Sox9 expression was reported to be increased in breast tumour samples after the development of resistance and overexpression of Sox9 in MCF7 cells was shown to confer resistance to tamoxifen in in vitro cell proliferation assays." (PMID 30622340, 2019). "To support this observation, we examined SOX9 mRNA levels in publicly available breast tumour datasets." (PMID 30622340, 2019). "Recent studies showed that SOX9 was highly expressed in breast tumor cells and tissues of basal type and that patients with higher SOX9 mRNA level had significantly shorter overall survival, thus supporting our data." (PMID 26930713, 2016). "In the later cohort, Pearson's analysis confirmed a strong correlation between HDAC9 and SOX9 expression in breast tumors (r=0.526, p<0.00001)." (PMID 26930713, 2016). "The significant correlation identified between SOX9 and breast tumor cell proliferation implies that SOX9 directly contributes to the poor clinical outcomes associated with invasive breast cancer." (PMID 25109818, 2014). "The accumulation of cytoplasmic SOX9 was detected in breast tissues of patients with invasive ductal carcinoma and lymph node metastasis and cytoplasmic SOX9 expression showed a significant correlation with increased cell proliferation of breast tumors." (PMID 35159173, 2022). "Furthermore, miR-140/SOX9/ALDH1 axis is important for basal-like breast tumor formation, BCSCs’ self-renewal and a potential therapy target for basal-like DCIS patients." (PMID 33413418, 2021). "CRISPR/Cas knockout of Sox9 reduces growth of tamoxifen-resistant breast tumours in vivo." (PMID 30622340, 2019). "We therefore determined whether Sox9 expression levels were altered in breast tumour samples using quantitative real-time PCR and western blotting." (PMID 30622340, 2019). "We show here that class IIa HDAC9 may be another regulator of SOX9 expression in breast tumor cells." (PMID 26930713, 2016). "We observed that the transcription factors EN1, SOX9 and PLAG1 were significantly higher expressed in basal-like breast tumours (which include approximately 80% TNBC), compared to the other breast tumour subtypes." (PMID 41505030, 2026). "The expression levels of Sox9 were found to be higher in breast tumors and the highest in TNBC samples, with the fractionated ALDH+ breast tumor cells possessing higher levels of Sox9 mRNA." (PMID 31394796, 2019). "Further analyses are needed of the 17(q22q25) duplication, which contains 482 genes including COL1A1, SOX9, RECQL5, and was described in specific subtypes of genomic changes in breast tumor and rhabdomyosarcoma." (PMID 29494553, 2018). "In addition, EN1, SOX9 and PLAG1 genes were significantly higher expressed in basal-like breast tumours." (PMID 41505030, 2026). "In addition, several papers have reported aberrant gene body methylation, including introns in cancer, e.g., hypermethylation of EGFR, LHX2, SOX9, and RFX1 introns in breast tumor tissue compared to paired adjacent tissue." (PMID 37296582, 2023).
diabetes (13 papers, 2011 to 2024). "Sox9 knockout animals exhibited glucose intolerance as they aged, mimicking the progressive loss of glucose homeostasis during diabetes." (PMID 38238288, 2024). "HNF1B is important during pancreas development where its mutation causes monogenic diabetes in humans, and functions upstream of SOX9 and NEUROG3 reflecting its late regulatory role during PP development." (PMID 36749553, 2023). "Additional studies are therefore required to determine whether mutations in Sox9 are associated with diabetes in humans." (PMID 21829703, 2011). "Glucose intolerance in Sox9-haploinsufficient mice suggests that mutations in Sox9 could play a role in diabetes in humans." (PMID 21829703, 2011). "A previous study demonstrated that pathologic ectopic bone after trauma was limited in the presence of diabetes, which may be explained by the impaired early Sox9 activation (chondrogenic differentiation) and late bone resorption by osteoclasts caused by diabetes." (PMID 32293797, 2020). "Ectopic overexpression of Sox9 in beta cells leads to cellular dedifferentiation and diabetes, with stunted expression of genes required for appropriate insulin secretion." (PMID 38238288, 2024). "Intriguingly, the inactivation of SOX9 and a relatively low Wnt signalling level are crucial for the maintenance of functional adult β-cells, as evidenced by a study that found that aberrant activation of Wnt signalling and SOX9 in adult β-cells resulted in diabetes mellitus." (PMID 37664185, 2023). "While we found a 50% reduction in Sox9 gene dosage to cause glucose intolerance in mice, Sox9+/Δpan mice did not develop overt diabetes." (PMID 21829703, 2011). "The viability of mice displaying pancreas-specific heterozygous loss of Sox9 afforded us the unique opportunity of studying the effects of reduced Sox9 dosage on pancreatic endocrine function in adult mice, to test whether Sox9 is a potential MODY or diabetes susceptibility gene." (PMID 21829703, 2011). "Sox9-haploinsufficient mice did not progress to overt diabetes, likely owing to a compensatory postnatal increase in beta-cell proliferation and mass observed in Sox9+/Δpan mice." (PMID 21829703, 2011). "While Tcf2-haploinsufficient humans display diabetes and severe pancreatic endocrine defects, partially mirroring our findings in Sox9+/Δpan mice, Tcf2+/− mice do not display diabetic symptoms." (PMID 21829703, 2011). "We previously reported that beta cell neogenesis from Sox9-expressing duct cells was observed in neither the physiological condition nor the regeneration process after injury, including partial pancreatectomy, cerulein-induced acute pancreatitis, streptozotocin diabetes or PDL, in Sox9CreERT2 mice." (PMID 25687338, 2015).
esophageal squamous cell carcinoma (13 papers, 2015 to 2025). Esophageal squamous cell carcinoma (ESCC) is a type of esophageal carcinoma (EC) that can affect any part of the esophagus, but is usually located in the upper or middle third. "In addition, in support of our assumption, another study on esophageal squamous cell carcinoma cell lines found that SOX9 is, at the same time, a downstream target as well as an upstream regulator of YAP signaling as they reported increased YAP protein levels after SOX9 knockdown." (PMID 32751354, 2020). "The positive correlation between the YAP signaling and SOX9 expression has been observed in esophageal squamous cell carcinoma, where YAP transcriptionally activates its downstream target SOX9." (PMID 36182943, 2022). "Similarly, the expression of B7-H4 correlated with stemness-related markers (i.e., CD44, SOX-2, SOX-9, OCT4) in NSCLC and esophageal squamous cell carcinoma (ESCC)." (PMID 41233805, 2025). "However, the clinical significance and biological role of SOX9 expression has not been characterized in human esophageal squamous cell cancer (ESCC)." (PMID 26384302, 2015).
acute kidney injury (12 papers, 2019 to 2025). Sudden and sustained deterioration of the kidney function characterized by decreased glomerular filtration rate, increased serum creatinine or oliguria. "Here, the authors have utilized kinome-wide screening approaches to reveal a pathogenic role of CDKL5 kinase in acute kidney injury, which is dependent on suppression of a SOX9-associated transcriptional network." (PMID 32317630, 2020). "SOX9-positive proximal tubular epithelial cells proliferate, expand, and differentiate to replace damaged tissue in acute kidney injury." (PMID 36613933, 2022). "Sox9+ stem cells have been reported to play an essential role in acute kidney injury (AKI)." (PMID 38801100, 2024). "In the context of immune-mediated repair, SOX9 emerges as a pivotal intrinsic molecular regulator in the renal epithelial regeneration response following acute kidney injury (AKI)." (PMID 41293317, 2025). "In models of acute kidney injury (AKI), SOX9 activation precedes the expression of kidney damage biomarkers, such as NGAL and KIM-1, suggesting a very early role in kidney damage." (PMID 36613933, 2022). "Adipose-derived stem cell exosomes (ADSCs-Exos) effectively counter renal injury caused by acute ischemia injury and attenuate chronic kidney disease (CKD) transition from acute kidney injury (AKI) by promoting tubular regeneration through activating Sox9 in renal tubular epithelial cells." (PMID 32149094, 2020). "Following acute kidney injury (AKI), 10.6% of proximal tubular cells expressed SOX9." (PMID 40563434, 2025).
cholangiocarcinoma (12 papers, 2017 to 2024). A carcinoma that arises from the intrahepatic biliary tree (intrahepatic cholangiocarcinoma) or from the junction, or adjacent to the junction, of the right and left hepatic ducts (hilar cholangiocarcinoma). "Indeed, we observed that not only the cholangiocarcinoma compartment but also some of the HCC tumors in all three genotypes stained positive for SOX9, a marker associated with less differentiated hepatocytes." (PMID 37627221, 2023). "Although we have fully demonstrated that HCG18 was potential marker for cholangiocarcinoma and contributed to tumor growth and metastasis through mediating miR-424-5p/SOX9 axis through PI3K/AKT pathway." (PMID 36854894, 2023). "More specificly, miR-424-5p target to SOX9 contributed to cholangiocarcinoma growth and metastasis through mediating miR-424-5p/SOX9 axis through PI3K/AKT pathway." (PMID 36854894, 2023). "QRT-PCR determined SOX9 mRNA level in 60 pairs of cholangiocarcinoma tissues and cell lines (QBC939, HUCCT1, RBE, HCCC9810, HiBEC)." (PMID 36854894, 2023). "More specific, miR-424-5p targeted to SOX9 contributed to cholangiocarcinoma growth and metastasis through mediating PI3K/AKT pathway." (PMID 36854894, 2023). "Here, we aimed to discover the biological activity of lncRNA HCG18 in cholangiocarcinoma, and the possible interaction between miR-424-5p and Sox9 influencing cancer cell growth and metastasis." (PMID 36854894, 2023). "Exosome-derived lncRNA HCG18 could promote the growth and metastasis of cholangiocarcinoma cells through the miR-424-5p/SOX9 axis of the PI3K/AKT pathway." (PMID 38627703, 2024). "Our observation that SOX9 confers chemoresistance to cholangiocarcinoma through the activation of CHK1 and the expression of multiple drug resistance proteins might provide a light pointer for further investigation of this aspect." (PMID 30420613, 2018). "SOX9 has been identified as a crucial regulator in cholangiocarcinoma (CCA), where it promotes plays a significant role in enhancing the expression of FGF7 and FGFR2." (PMID 38491511, 2024). "Decreased miR-424-5p levels subsequently elevate the expression of SRY-box transcription factor 9 (SOX9) and activate the PI3K/AKT pathway, culminating in accelerated tumor progression in cholangiocarcinoma." (PMID 39161590, 2024). "No SOX9 mutation was found in the other six cancer types, including ACC, KICH (kidney chromophobe), LAML (acute myeloid leukemia), DLBC (diffuse large B-cell lymphoma), CHOL (cholangiocarcinoma), and TGCT." (PMID 37020558, 2023).
endometriosis (12 papers, 2014 to 2025). The growth of functional endometrial tissue in anatomic sites outside the uterine body. "Is endometriosis associated with abnormally located endometrial basalis-like (SSEA1+/SOX9+) cells in the secretory phase functionalis and could they contribute to ectopic endometriotic lesion formation?" (PMID 30496412, 2019). "In pathologic states such as endometriosis, SOX9 dynamics become disrupted; in 3D culture, ectopic epithelial cells self-organize into polarized gland-like structures displaying apical–basal SOX9 gradients, implicating its role in morphogenetic regulation." (PMID 41153718, 2025). "Women with endometriosis have more SSEA-1+SOX9+ epithelial cells in their functionalis compared to normal women." (PMID 33898428, 2021). "SOX9, a marker of stem/progenitor activity in other tissues, is normally expressed in the basalis, but women with endometriosis exhibit a higher number of SSEA-1+SOX9+ cells in the functionalis during the secretory phase of the menstrual cycle." (PMID 33898428, 2021). "In contrast, SOX9 mRNA levels were significantly higher in tissue from women with endometriosis (median=1.2, IQR = 0.85–1.7, n = 6) compared with the healthy fertile control samples (median 0.2, IQR = 0.2–1, n = 3, P < 0.05)." (PMID 30496412, 2019). "The chronological changes occurring in the eutopic endometrium with induction of ectopic endometriotic lesions were examined in the baboon, where induction of endometriosis resulted in a trend to increased SOX9+ cells in eutopic endometrium." (PMID 30496412, 2019). "This study examines the involvement of SSEA1+SOX9+ basalis-like epithelial cells derived from eutopic endometrium in the pathogenesis of endometriosis." (PMID 30496412, 2019). "Interestingly, CCC cancer cells displayed transcriptional similarity to glandular secretory, ciliated, and SOX9+ LGR5+ epithelial found in endometriosis conditions." (PMID 39149248, 2024). "Additionally, endometrial epithelial cells with a basalis-like phenotype (SSEA-1+ and SOX9+) are enriched in women with endometriosis." (PMID 32570847, 2020). "Interestingly, establishing endometriosis in a baboon model by transplanting curetted endometrium during spontaneous menstruation caused an increase in the appearance of basalis like SSEA-1 and SOX9 positive epithelial cells in the functionalis of the animals." (PMID 32570847, 2020). "The transcriptionally closest epithelial cells were glandular secretory, SOX9+ LGR5+ epithelial cells and ciliated in the eutopic endometrium of donors with endometriosis." (PMID 39149248, 2024). "Endometrial basalis cells with progenitor potential are postulated to play a role in the pathogenesis of endometriosis and SSEA1 and nuclear SOX9 (nSOX9) mark basalis epithelial cells that also have some adenogenic properties in vitro." (PMID 30496412, 2019). "We have shown that the eutopic endometrial functionalis epithelium of women with endometriosis, aberrantly contain an increased number of cells with SSEA1+SOX9+ basalis-like epithelial cell phenotype." (PMID 30496412, 2019). "Specifically, some key regulators from the miR-449 and miR-34b/c cluster, miR-200 family, miR-106a-363 cluster, miR-182/183, FOX family, GATA family, and E2F family as well as CEBPA, SOX9 and HNF4A were suggested to play vital regulatory roles in the pathogenesis of endometriosis." (PMID 29357938, 2018). "Interestingly, cells in ectopic endometriosis lesions also expressed SSEA-1 and nuclear SOX9, and SOX9 and SSEA-1 expression patterns were similar to those in the matched eutopic basalis epithelia." (PMID 26056600, 2014).
pancreatic ductal adenocarcinoma (12 papers, 2015 to 2025). An infiltrating adenocarcinoma that arises from the epithelial cells of the pancreas. "In this work we found that an increased expression of the developmental factor SOX9 is associated with metastasis, a poor prognosis and resistance to therapy in pancreatic ductal adenocarcinoma patients and in cell cultures." (PMID 35205666, 2022). "They expressed several tetraspanins, which are involved in the regulation of stemness in other cell types, including Tspan8 that is upregulated by SOX9 in pancreatic ductal adenocarcinoma in response to EGF stimulation." (PMID 37408269, 2023). "In pancreatic ductal adenocarcinoma, both SOX9 and GLI1 are important to maintain the malignant phenotype of cancer stem cells." (PMID 29659575, 2018). "By lineage tracing, their study also suggested that upon the expression of SOX9, pancreatic intraepithelial neoplasia (PanIN) lesions and subsequently pancreatic ductal adenocarcinoma arise from ductal metaplasia of the pancreatic acinar cells, a phenomenon known as acinar-to-ductal metaplasia." (PMID 35227293, 2022). "SOX9 is upregulated in the majority of pancreatic ductal adenocarcinoma cases." (PMID 35884771, 2022). "In a liver metastasis model of PDAC (pancreatic ductal adenocarcinoma), treatment with a NTN1-neutralizing antibody or tumoral knockdown of Neo1 reduced ZEB1 and SOX9 and decreased tumor progression." (PMID 40777309, 2025). "In pancreatic ductal adenocarcinoma (PDAC), another KRAS‐driven cancer, SOX9 is a critical mediator of KRAS‐induced PDAC initiation of pancreatic acinar cells in mouse model." (PMID 34919787, 2022). "Treatments induced apoptosis, increased BAX/BCL-2 ratio and suppressed the expression of SOX9 and SOX18, genes shown to be significantly up-regulated in pancreatic ductal adenocarcinoma." (PMID 35408514, 2022). "Interestingly, lack of METTL14 leading to increased expression of duct markers such as KRT19, SOX9, MEIS2 could have implications for pancreatic ductal carcinoma which is among the most lethal cancers in humans." (PMID 39322760, 2024).